PAX6 (paired box 6)
Diseases named in the same sentence as PAX6 in open-access papers (continued):
Sharing a sentence is not in itself a finding about the gene and the disease.
polymicrogyria (2 papers, 2009 to 2023). A developmental brain abnormality characterized by an excessive amount of small convolutions on the surface of the brain and cognitive dysfunction. "In patients with PAX6 mutation, polymicrogyria, absence of pineal gland, and lack of the anterior commisure have all been reported." (PMID 19898691, 2009).
retinal detachment (2 papers, 2021 to 2023). An eye emergency condition which may lead to blindness if left untreated. "Retinal detachment was recorded in 9 eyes (5.2%) from 6 individuals, representing a deletion of the PAX6 3′ regulatory region, a nonsense variant (2 unrelated patients with p.[Arg240*]), CTE (p.[Asp413Glufs*112] and p.[*423Leuext*14]), and an intronic mutation (c.357+5G>A)." (PMID 34101622, 2021).
rhabdomyosarcoma (2 papers, 2012 to 2016). A rare aggressive malignant mesenchymal neoplasm arising from skeletal muscle. "Interestingly, it was found that RD cells of smooth muscle rhabdomyosarcoma origin displayed relatively high expression of both early neural differentiation markers: (PAX6, Musashi1, & βIII-tubulin, as well as the mature neural differentiation markers NCAM and NSE." (PMID 26738773, 2016).
Saethre-Chotzen syndrome (2 papers, 2016 to 2019). Saethre-Chotzen syndrome (SCS) is an inherited craniosynostosis syndrome characterized by unilateral or bilateral coronal synostosis, facial asymmetry, ptosis, strabismus and small ears with prominent crus, among other less common manifestations. "In four cases, patients’ phenotypes well matched to the syndromic features caused by haploinsufficiency of PAX6 (Aniridia, MIM:607108), TCF4 (Pitt-Hopkins syndrome, MIM:610954), FBN1 (skeletal/joint malformations, limb deformity; MIM:154700), and TWIST1 (Saethre-Chotzen syndrome, MIM:101400)." (PMID 27257017, 2016).
senile cataract (2 papers, 2020 to 2021). A cataract with no obvious cause occurring in persons over 50 years old. "Among sumoylation substrates, we have also demonstrated that the contrast stability of p46 and p32 Pax6 can be used as another molecular marker for senile cataract." (PMID 34425033, 2021). "From these studies, we conclude that Ubc9, SENP6, and p32 Pax6 can be used as molecular markers for simple senile cataracts." (PMID 32827359, 2020). "In contrast, sumoylation of p32 Pax6 is observed in senile cataracts and increases its stability." (PMID 32827359, 2020).
Sjögren’s syndrome (2 papers, 2013 to 2021). "In subsequent studies, we noted the down-regulation of paired box gene 6 (Pax6) in both human patients with chronic KCS associated with Sjögren’s syndrome and Aire KO mice." (PMID 24143217, 2013). "PAX6 was downregulated due to inflammation in a Sjögren’s syndrome model, the Aire mouse, and this led to keratinization." (PMID 34769520, 2021).
tauopathies (2 papers, 2020 to 2022). "Thus, to discriminate the two tauopathies, we hereby propose JUN(B,D)HIGH, FOS(L1,L2)HIGH as well as the involvement of DUX4, KLF5, MAX::MYC, PAX6, and PPARG to support the identity of CBD-originated astrocytes." (PMID 35976433, 2022). "ADNP showed relatively reduced expression in the ADNP syndrome cerebellum, which was also observed for 25 additional genes (representing >50% of the tested genes), including NLGN1, NLGN2, PAX6, SMARCA4, and SNAP25, converging on nervous system development and tauopathy." (PMID 32661233, 2020).
Anisometropia (1 paper, 2024). Inequality of refractive power of the two eyes. "Recently, PAX6 and ZFHX1B variants were reported to be involved in developmental anisometropia through regulating the unbalanced elongation of axial length between the eyes." (PMID 38243264, 2024).
astrocytic tumor (1 paper, 2010). A glial tumor of the brain or spinal cord showing astrocytic differentiation. "Interestingly, most of the astrocytic tumor samples showed low expression levels of PAX6 even though GLI1 was expressed at high levels." (PMID 21059263, 2010). "A majority of the cell lines displayed low levels of PAX6 despite high GLI1 expression, as was similarly seen in primary astrocytic tumor samples." (PMID 21059263, 2010). "Thus, GLI1 does not appear to up-regulate PAX6 expression in astrocytic tumors." (PMID 21059263, 2010).
Au-Kline syndrome (1 paper, 2024). "Thus, we tested the phase separation ability of the three proteins, PQBP1 in Renpenning syndrome, HNRNPK in Au-Kline syndrome, and PAX6 in Aniridia." (PMID 38225666, 2024).
autoimmune disorders (1 paper, 2013). "Our results suggest that adjuvant gene therapy with Pax6 may compliment anti-inflammatory agents as a novel therapeutic approach to prevent SQM in autoimmune disorders of the ocular surface." (PMID 24143217, 2013).
brain infarct (1 paper, 2023). "Of note, the upregulated miR-365 expression led to augmented neurological deficits and brain infarct size by reducing the level of PAX6 expression and the number of newly mature neurons derived from astrocytes in the ischemic striatum." (PMID 37840919, 2023).
corneal ulcer (1 paper, 2021). Area of epithelial tissue loss from corneal surface; associated with inflammatory cells in the cornea and anterior chamber. "Loss of interferon regulatory factor 1 and PAX6 induced by FOXC1 dysfunction is linked to the corneal ulcer." (PMID 33414365, 2021). "Loss of FOXC1, IRF1, and PAX6 was observed in some regions of the corneal ulcer tissues." (PMID 33414365, 2021). "FOXC1-depleted LSCs show the activation of an epidermis-specific gene program and the repression of IRF1 and PAX6, which are pathological characteristics of the human corneal ulcer." (PMID 33414365, 2021).
cortical cataract (1 paper, 2021). A cataract (disease) that involves the lens cortex. "The three unrelated aniridia patients with PAX6 variants (patient ID 1-1, 13-1 and 25-1) had posterior subcapsular, posterior cortical and cortical cataracts, respectively." (PMID 33494148, 2021).
edema (1 paper, 2020). An abnormal accumulation of fluid beneath the skin, or in one or more cavities of the body. "Second, we forced PAX6 expression in corneal endothelium that could alleviate the corneal edema induced by injuries via improving the “barrier” function." (PMID 32826860, 2020).
Ehlers-Danlos syndrome (1 paper, 2010). The Ehlers–Danlos syndromes (EDS) are a clinically and genetically heterogeneous group of heritable connective tissue disorders (HCTDs) characterized by joint hypermobility, skin hyperextensibility, and tissue fragility. "Other possible candidates are the type V collagen genes COL5A1and COL5A2 involved in Ehlers-Danlos syndrome (EDS), fibrillin-1 gene (FBN1) responsible for Marfan syndrome, PAX6 associated with aniridia and FOXC1 associated with abnormal ocular development." (PMID 20485516, 2010).
eye infection (1 paper, 2022). An infectious process affecting any part of the eye. "Since, Pax6 is involved in eye development and is highly expressed in various eye tissues, using the Pax6-Cre system to delete SPP in the eye makes an excellent model to study eye infection in our model of ocular HSV infection." (PMID 36215312, 2022). "All 39 infected mice in the Pax6-SPP-/- group survived ocular infection, while 28 of 31 mice in the WT control group survived ocular infection (p>0.05; ANOVA)." (PMID 36215312, 2022). "Similar to global SPP depletion by tamoxifen treatment and the absence of SPP in peripheral sensory neurons of Avil-SPP-/- mice, the absence of SPP in the eyes of infected Pax6-SPP-/- mice did not affect their susceptibility to ocular infection with the virulent HSV strain McKrae." (PMID 36215312, 2022).
folate deficiency (1 paper, 2019). A nutritional condition produced by a deficiency of FOLIC ACID in the diet. "Using ChIP-seq and RNA-seq assays, we demonstrated that an increase in H2AK119ub1 level downregulated the expression of the NTC-related genes Cdx2, Nes, Pax6, and Gata4 in mESCs under conditions of folate deficiency." (PMID 31722724, 2019).
foveal hypoplasia 1 (1 paper, 2021). Any foveal hypoplasia in which the cause of the disease is a mutation in the PAX6 gene. "Differential diagnoses includes autosomal dominant foveal hypoplasia-1 (FVH1, OMIM #136520), also referred to as foveal hypoplasia-1 with or without anterior segment anomalies and/or cataract, which is caused by heterozygous missense variants in the PAX6 gene on chromosome 11p13." (PMID 33498813, 2021).
ganglioglioma (1 paper, 2023). A well differentiated, slow growing neuroepithelial neoplasm composed of neoplastic, mature ganglion cells and neoplastic glial cells. "Co-expression of CD34, PAX6, SOX2, and MSI1 (after stringent counter selection against vascular cells using PECAM1, VWF, DCN, and COL1A2), was particularly strongly associated with ganglioglioma neoplastic cell stemness." (PMID 36966348, 2023). "PAX6, MEIS1, and TCF7L2 concentrations as well as SCENIC-calculated regulon scores correlated strongly with ganglioglioma neoplastic cell stemness by CellRank/CytoTRACE pseudotime or SCENT signaling entropy rate." (PMID 36966348, 2023).
GM1 gangliosidosis (1 paper, 2020). A rare lysosomal storage disorder characterized biochemically by deficient beta-galactosidase activity and clinically by a wide range of variable neurovisceral, ophthalmological and dysmorphic features. "To assess the cellular phenotypes present in GM1 gangliosidosis, we first differentiated the disease-derived iPSC lines into NSCs expressing specific markers, SOX1, PAX6, and NESTIN." (PMID 32302553, 2020).
HCMV infection (1 paper, 2013). "While expression of the NSPC markers Sox2 and Pax6 were kept at high levels following HCMV infection, that of another NSPC marker Nestin was markedly suppressed at 7 dpi." (PMID 24144363, 2013).
hereditary glaucoma (1 paper, 2017). Hereditary glaucoma is a clinically diverse group of rare eye disorders with genetic predisposition characterized by elevated intraocular pressure (IOP) and glaucomatous changes of the optic nerve head, leading to field defects, visual loss and blindness. "Transgenic mice overexpressing Norrin in the retina (Pax6-Norrin) were generated and crossed with DBA/2J mice with hereditary glaucoma and optic nerve axonal degeneration." (PMID 29079753, 2017).
Hyperinsulinemia (1 paper, 2025). An increased concentration of insulin in the blood. "Hyperinsulinemia markedly upregulates the master transcription factor PAX6, which in turn represses cell-cycle inhibitor p27." (PMID 41155220, 2025).
insomnia (1 paper, 2011). A sleep disorder characterized by difficulty in falling asleep and/or remaining asleep. "Hence, dysregulation of ROR1, PLCB1, or PLCB4 by PAX6 and CTCF may be one mechanism that links neural and pancreatic dysfunction not only in insomnia but also in the relevant psychiatric disorders that are accompanied with circadian rhythm disruption and metabolic syndrome." (PMID 21494683, 2011).
iris diseases (1 paper, 2021). "In this study, we just have screened protein-coding region of 37 genes associated iris diseases but ignored conserved non-coding element and CNV of PAX6, which should be improved in the future." (PMID 34016071, 2021).
iron deficiency (1 paper, 2024). "We found that iron deficiency induced by Sev suppressed Ki67 expression and DNA replication in NPCs by decreasing BrdU+ and Pax6+ colocalization in cortex and hippocampus indicating that Sev inhibited the NPCs proliferation." (PMID 38334030, 2024).
ischemic stroke (1 paper, 2018). A stroke disorder caused by obstruction of blood flow to the brain, due to thrombotic (local blood clot formation) or embolic (due to a blood clot or other material traveling from another site) event. "Our results demonstrate that increase of miR‐365 in the ischemic brain inhibits astrocyte‐to‐neuron conversion by targeting Pax6, whereas knockdown of miR‐365 enhances PAX6‐mediated neurogenesis from astrocytes and attenuates neuronal injury in the brain after ischemic stroke." (PMID 29451327, 2018). "Therefore, we proposed that miRs might regulate the conversion of astrocytes into neurons via directing PAX6 expression in the brain after ischemic stroke." (PMID 29451327, 2018).
lens agenesis (1 paper, 2018). "SOX2 and PAX6 mutations may cause lens induction failure, FOXE3 mutations are associated with lens agenesis, and OTX2, CHX10, and RAX may cause failure of retinal differentiation." (PMID 30153864, 2018).
lung adenocarcinoma (1 paper, 2021). A carcinoma that arises from the lung and is characterized by the presence of malignant glandular epithelial cells. "However, PAX6 can act as an oncogene for cancer stemness induction in lung adenocarcinoma." (PMID 34459131, 2021).
macular corneal dystrophy (1 paper, 2011). Macular corneal dystrophy (MCD) is a rare, severe form of stromal corneal dystrophy characterized by bilateral ill-defined cloudy regions within a hazy stroma, and eventually severe visual impairment. "As well as the well-documented epithelial defects, aberrant Pax6 dosage had profound effects on the corneal stroma and endothelium in both genotypes, including cellular vacuolation, similar to that reported for human macular corneal dystrophy." (PMID 22220198, 2011).
mammary adenocarcinoma (1 paper, 2011). "The mammary adenocarcinoma cell line GFP-AR 3108 stably expressing GFP-AR was transiently transfected with plasmids expressing Cherry-Pax6 or Cherry-SPBP (respectively)." (PMID 21935435, 2011).
medullary carcinomas of the thyroid (1 paper, 2024). "The PAX8 positivity rates of 0–75% reported earlier for medullary carcinomas of the thyroid may to some extent be caused by PAX8 antibodies cross-reacting with PAX6." (PMID 39105782, 2024).
memory impairment (1 paper, 2024). "Collectively, these findings indicate that downregulating PAX6 can also ameliorate memory impairments and AD-like pathologies in 5xFAD mice." (PMID 38679634, 2024).
meningioma (1 paper, 2022). A generally slow growing tumor attached to the dura mater. "Additionally, hypermethylated markers in high-grade meningiomas included proximal promoters of PAX6 and PCDH genes, in addition to correlation with proliferation markers." (PMID 36551712, 2022). "Along with other candidates also associated with WHO grades, such as SMC4 (three hits, NC) and PAX6 (four hits, PC), these genes may constitute other interesting progression biomarkers in meningiomas." (PMID 36551712, 2022). "Candidates such as DOK7 (3 hits, NC), the PCDH clusters (32 hits, PC), PAX6 (15 hits, PC), and TBR1 (6 hits, PC), among others with dynamic and island-restricted CpGs, constitute potential proliferative biomarkers in meningiomas." (PMID 36551712, 2022).
metastatic prostate carcinoma (1 paper, 2024). A carcinoma that arises from the prostate gland and has spread to other anatomic sites. "We also found that the PAX6 expression was significantly higher in metastatic PCa tissues than that in non-metastatic prostate carcinoma in the GSE35988 dataset and the GSE3325 dataset." (PMID 38745318, 2024).
multiple endocrine neoplasia type 1 syndrome (1 paper, 2020). "Of those patients, one who had von Hippel-Lindau disease was classified into the low PAX6 expression group, and the other patient with multiple endocrine neoplasia type 1 syndrome was classified into the high PAX6 expression group." (PMID 33182335, 2020).
neuroendocrine carcinoma (1 paper, 2024). A malignant neuroendocrine neoplasm composed of cells containing secretory granules that stain positive for NSE and chromogranin. "Next we hypothesized that high expression of PAX6 might be generalized in other neuroendocrine cancers, and we examined expression of PAX6 in SCLC that is also a type of neuroendocrine and compared it to non-small cell lung cancer (NSCLC)." (PMID 38745318, 2024).
neuropathy (1 paper, 2022). A disorder affecting the nervous system that manifests with pain, tingling, numbness, and/or muscle weakness. "Paired box 6 (PAX6) is a multifunctional transcription factor that regulates the expression of genes involved in cell proliferation, differentiation, inflammation, oxidative stress, and neuropathy." (PMID 35204186, 2022).
Noonan syndrome (1 paper, 2021). Noonan Syndrome (NS) is characterized by short stature, typical facial dysmorphism and congenital heart defects. "In our cohort of fetuses, the CDG-2m, RyR1-related myopathy, Noonan syndrome, and possibly the mosaic PAX6 duplication might have been detected with prenatal WES." (PMID 34733861, 2021).
oral cancer (1 paper, 2020). "IL-6 also induced promoter hypermethylation of several important TSGs, namely CHFR, GATA5, and PAX6, in oral cancer cells." (PMID 32678024, 2020).
oral squamous cell carcinoma (1 paper, 2023). "Specifically, SNHG17 upregulates PAX6 to facilitate the development of oral squamous cell carcinoma, stimulates SOX4 to promote the epithelial-mesenchymal transition in ESCC cells, and activates H2AX-associated signaling pathways to promote the development of renal cell carcinoma." (PMID 37231440, 2023).
pancreatic NETs (1 paper, 2022). "CDX2 is also expressed in around 15% of pancreatic NETs with co-expression of pancreatic markers such as Islet 1 (ISL1) and PAX-6/8." (PMID 35626118, 2022). "For lung NETs, the 10% of midgut CDX 2-negative tumours, and the 5–10% of PAX6/ISL1 negative pancreatic NETs, other markers should be determined." (PMID 35626118, 2022).
pancreatic neuroendocrine neoplasm (1 paper, 2020). A neoplasm with neuroendocrine differentiation that arises from the pancreas. "This study aimed to examine dynamic computed tomography (CT) features for predicting pancreatic neuroendocrine neoplasms (Pan-NENs) with low PAX6 expression." (PMID 33182335, 2020).
pancreatitis (1 paper, 2021). Inflammation of the pancreas. "The PAX6 gene appears to play an important role in pancreas development therefore, the PAX6 deletion may represent an underlying risk for development of pancreatitis in patients with WAGR spectrum." (PMID 34970513, 2021).
sensorineural deafness (1 paper, 2018). "In addition, mutations in KCNQ4 and STRC can induce sensorineural deafness, but this has not been found with PAX6." (PMID 29922125, 2018).
sleep disorder (1 paper, 2022). A change from the patient's baseline sleeping pattern, in the hours slept and/or an alteration/dysfunction in the stages of sleep. "Detailed investigation of Pax6-circadian clock gene regulation in the eyes and brain will shed further light on the pathogenesis of ASD and comorbid sleep disorders." (PMID 35682795, 2022).
spina bifida (1 paper, 2022). A congenital neural tube defect in which vertebrae are not fully formed. "Our data suggest that this process is altered in fetuses with spina bifida due to modifications in Pax6, Olig2, and Nkx2.2 expression throughout the time points studied." (PMID 35782393, 2022). "Specifically, we observed an upregulation of Pax6 and Nkx2.2 gene expression and an elevated number of Pax6 or Nkx2.2 positive cells in spina bifida fetuses compared to the control groups." (PMID 35782393, 2022). "Based on our data, we propose that NPCs become committed to the astrocyte lineage due the direct exposure to the amniotic fluid in spina bifida by dysregulation in patterning factors, Pax6, Olig2, and Nkx2.2 and potentially downregulating neurogenesis and oligodendrogenesis." (PMID 35782393, 2022). "Therefore, to assess the impact of RA-induced spina bifida on NPC differentiation, we characterized Pax6, Olig2, and Nkx2.2 expression in fetal spinal cords during gestation because in spina bifida the spinal cord is open and unfolded exposing the VZ and the progenitor cells to the amniotic fluid." (PMID 35782393, 2022). "Importantly, we demonstrate a possible implication of Pax6, Nkx2.2, and Olig2 transcription factors, as well as factors in the Notch-BMP signaling pathway, in the premature shift of NPCs into astrocytes in fetuses with RA-induced spina bifida." (PMID 35782393, 2022).